NOX5 (NADPH oxidase 5)
Diseases named in the same sentence as NOX5 in open-access papers (continued):
Sharing a sentence is not in itself a finding about the gene and the disease.
diabetes (22 papers, 2014 to 2026). "The present study is the first to establish associations between polymorphisms in NOX5 and the risk of type 2 diabetes mellitus, and provides a new line of evidence for the crucial role of oxidative stress-related genes in disease susceptibility." (PMID 39529984, 2024). "Renal inflammation in diabetes has been linked to NOX5, particularly via activation of the TLR-4-dependent pathway." (PMID 38671844, 2024). "The combination of Nox5 expression and diabetes was associated with a significant increase in aneurysm incidence compared to non-diabetic Nox5 expressing mice (p < 0.01)." (PMID 35798762, 2022). "Overall, these findings have revealed that the genes encoding P67PHOX/P47PHOX/NOX2, NOX4, and NOX5 contribute to hypertension‐ and diabetes‐induced renal injury by altering the renal production of ROS." (PMID 33377622, 2021). "Recent studies suggest that Nox5, either alone or together with Nox4, is predominantly responsible for the pathogenic renal ROS production in diabetes." (PMID 33396868, 2020). "The upregulation of NOX5 is implicated in several pathological conditions, including hypertension, diabetes, inflammation, and fibrosis, making it a promising target for improving cardiovascular and renal outcomes in diabetes." (PMID 40076813, 2025). "In patients with diabetes, there is an increased expression of renal NOX5 associated with enhanced ROS formation and the upregulation of ROS-sensitive pathways as early growth response 1 (EGR-1), protein kinase C-α (PKC-α), and thioredoxin-interacting protein (TXNIP)." (PMID 36905456, 2023). "Nox4 has been implicated in renal injury in mouse models of diabetes, effects that are ameliorated with Nox1/4 inhibitors and in mice deficient in Nox4.54, 55 Nox5 may also be important in diabetes-associated vascular injury and nephropathy." (PMID 29459239, 2018). "Studies show that NADPH oxidases (NOX), particularly the Nox4 and Nox5 isoenzymes, are the primary contributors to ROS production in diabetic kidneys." (PMID 40864768, 2025). "Recently, we and others have reported that the overexpression of human NOX5 in podocytes and smooth muscle cells (mesangial cells) promotes renal damage in diabetes." (PMID 38671844, 2024). "Since NOX4 and NOX5 are both endogenously expressed in humans, we examined if Nox4 deletion is sufficient to protect against kidney damage in diabetes in the presence of NOX5 expression." (PMID 38671844, 2024). "Recent studies, including our own, have clearly demonstrated the increased expression of renal NOX5 in individuals with diabetes." (PMID 38671844, 2024). "In human kidney biopsies, Nox5 was found to be expressed in mesangial cells of glomeruli and appeared to be upregulated in diabetes." (PMID 37242602, 2023). "This remarkable finding agrees with our results in diabetic mice, where the diabetes-induced overexpression of fibronectin was prevented by knocking in Nox5." (PMID 35798762, 2022). "Although unlikely, we cannot exclude that changes in Nox2 expression also play a role in the NOX5-induced aortic aneurysms in diabetes, however, further studies, e.g., focusing on NOX2 protein levels, are needed to support this conclusion." (PMID 35798762, 2022). "In human kidney biopsies, NOX5 was found to be expressed in glomeruli, especially in podocytes and mesangial cells, which appeared to be increased in diabetes." (PMID 33377622, 2021). "This review describes the key roles of Nox2 and Nox4, as well as Nox1 and Nox5, in glucose homeostasis, endothelial function and oxidative stress, with a key focus on how they are regulated in health, and dysregulated in type 2 diabetes mellitus." (PMID 34571964, 2021). "Growing evidence suggest that the members of the pro-oxidant Nox family, particularly Nox4 and Nox5 isoforms, are the key contributors of renal ROS generation in diabetes." (PMID 33396868, 2020).
diabetes (continued). "Together, these studies in humanized Nox5 mice suggest an important role for Nox5 in vascular injury and progression of nephropathy in diabetes." (PMID 30334629, 2019). "Summer in both species and diabetes in rats downregulated myocardial Nox4 while reciprocally upregulating Nox2 and Nox5 in guinea‐pigs, and Nox2 in rats." (PMID 29084841, 2017). "Silencing Nox5 reduces ROS production and alleviates inflammation and fibrosis induced by diabetes." (PMID 40864768, 2025). "Overexpression of NOX5 leads to cancers, diabetes, and cardiovascular diseases." (PMID 38734761, 2024). "Expanding on previous findings, this study examined the role of endothelial cell-specific NOX5 expression in an STZ-induced insulin-deficient diabetes mouse model in the presence or absence of NOX4 expression." (PMID 38671844, 2024). "In relation to metabolic diseases, several works have analyzed the effect of NOX5 in diabetes." (PMID 36905456, 2023). "Indeed, increased expression of renal Nox4 and Nox5 have been demonstrated in the human diabetic kidney, as well as in renal cells, in response to high glucose and diabetes-induced AGE accumulation, angiotensin II and TGF-β." (PMID 33396868, 2020). "However, experimental studies using humanized Nox5 transgenic mice models demonstrate accelerated renal injury in diabetes, mimicking the human situation where Nox5 is a critical mediator in the pathogenesis of DKD." (PMID 33396868, 2020). "NOX-5 was found to be upregulated in diabetes, hypertension, and human atherosclerotic lesions; however, recently it is described that NOX-5 has an important role in angiotensin II-induced vascular dysfunction and remodeling, but not in the development of hypertension." (PMID 31766727, 2019). "Recently, it has been demonstrated that upregulated Nox5-derived ROS aggravate diabetes-induced renal failure by enhancing the expression of inflammatory molecules, excess synthesis of extracellular matrix components, and increased glomerular Mac infiltration in a human Nox5 transgenic mouse model." (PMID 31565149, 2019). "Moreover, in transgenic mice with podocyte-specific expression of human Nox5, renal injury was amplified by diabetes." (PMID 29459239, 2018). "In summary, our study reveals that PKCα is the primary isoform mediating the activation of Nox5 and this maybe of significance in our understanding of the vascular complications of diabetes and other diseases with increased ROS production." (PMID 24505490, 2014). "In addition, vascular smooth muscle cell/mesangial cell-specific overexpression of Nox5 in a mouse model of diabetic nephropathy worsened diabetes-induced albuminuria, renal hypertrophy, mesangial expansion, ECM accumulation, glomerulosclerosis, and renal inflammation via increased ROS generation." (PMID 37242602, 2023). "Nox5 transgenic mice with podocyte-specific expression of human Nox5 exhibited increased renal ROS production, glomerular injury and tubulointerstitial fibrosis, albuminuria, and elevated blood pressure, phenomena that are exacerbated in the presence of diabetes." (PMID 30334629, 2019). "Previously, it has been shown in murine models of diabetes that the blockade of NOX4 leads to a reduction in albuminuria and that the overexpression of human NOX5 in podocytes and mesangial cells of diabetic mice exacerbates albuminuria." (PMID 38671844, 2024). "A recent study transfected human NOX5 selectively in endothelial cells and VSMC of diabetic mice and demonstrated that diabetes leads to upregulation of both endothelial and VSMC NOX5 expression." (PMID 31382355, 2019). "While NOX2 predominates in immune cells and has been our focus here, it's worth noting that other members of the NOX family, particularly NOX5, also play important roles in vascular cells, and the broader family of NADPH oxidases contributes to various aspects of vascular pathology in diabetes." (PMID 41607455, 2026).
diabetes (continued). "However, in humans, we and others have recently identified the potentially more important NADPH-oxidase isoform, NOX5, as a major player in DKD, and potentially in other complications of diabetes, including cardiovascular disease (CVD) and retinopathy." (PMID 38671844, 2024). "Nox5 is present in humans but not in rodents and therefore it has been difficult to study the role of Nox5 in conventional rodent models of diabetes." (PMID 34829831, 2021). "To explore the significance of this pathway in diabetes, we next measured superoxide production in COS-7 cells expressing Nox5 exposed to high glucose (D-Glucose, 25 mM) or osmotic control (L-Glucose, 25 mM) in the presence and absence of a more selective PKCα inhibitor, Go 6976." (PMID 24505490, 2014). "Finally, based on the clinical observations of Nox5 levels correlating with aortic aneurysms, we investigated whether Nox5 induces aortic aneurysm under atherosclerotic conditions with and without diabetes." (PMID 35798762, 2022). "The main focus of this study was to identify whether NOX5 overexpression in endothelial cells (EC-NOX5), a key component of the glomerular filtration barrier, induces renal pathology, particularly renal inflammation and EMT-related fibrosis in the presence or absence of diabetes." (PMID 38671844, 2024).
Hypertension (16 papers, 2017 to 2025). The presence of chronic increased pressure in the systemic arterial system. "Specifically, we delineate NOX5 as a major source of O2− and H2O2 in human VSMCs and demonstrate that in hypertension NOX5 is associated with activation of redox-sensitive signalling pathways, processes regulated by c-Src." (PMID 34320175, 2022). "The role of NOX5 in hypertension-associated vasculopathy is unclear because rodents, the most common model used to study hypertension, lack NOX5 gene." (PMID 34320175, 2022). "Here, we investigated the role of NOX-induced oxidative stress in VSMCs in human hypertension focusing on NOX5, and explored c-Src, as a putative intermediate connecting NOX5-ROS to downstream effector targets underlying VSMC dysfunction." (PMID 34320175, 2022). "Associated with NOX5-induced VSMC oxidative stress in hypertension was increased post-translational modification of downstream signalling targets." (PMID 34320175, 2022). "This study applies network medicine to identify a subgroup of patients with NADPH oxidase 5-induced uncoupling of nitric oxide synthase as the cause of age-related hypertension, enabling a first-in-class mechanism-based treatment of hypertension." (PMID 33170835, 2020). "The recent GWAS highlighting the association between the Nox5 gene and hypertension is certainly interesting and provides a credible foundation for further investigation of Nox5 in human cardiovascular disease." (PMID 30334629, 2019). "Clinically, a putative role for NOX5 in hypertension was recently unravelled in a genome‐wide association study searching for novel blood pressure‐associated genes." (PMID 30801870, 2019). "Kidney NOX5 expression and activity are increased in patients with essential hypertension, and NOX5 is likely to be a major cause of renal oxidative stress in hypertension (Holterman, Thibodeau, & Kennedy, 2015)." (PMID 30801870, 2019). "Nox1, Nox2, Nox4, and Nox5 of the Nox family are associated with oxidative stress in hypertension." (PMID 39974735, 2025). "In the case of the brain, the works from the group of Harald Schmidt associate the expression of human NOX5 in endothelial and hematopoietic cells in a knock-in mouse model and in vitro organotypic hippocampal cultures, with the presence of hypertension and the risk of stroke." (PMID 36905456, 2023). "Modulating the NOX5/ROS/c-Src pathway may have therapeutic potential by targeting redox signalling pathways involved in vascular dysfunction associated with hypertension." (PMID 34320175, 2022). "To test this causal endothelial NOX5 hypothesis for human hypertension, we enrolled consecutive outpatients with essential hypertension and a baseline estimated glomerular filtration rate (eGFR) ≥30 mL/min/1.73 m2." (PMID 33170835, 2020). "NOX5 has also been implicated in the development of hypertension." (PMID 30801870, 2019). "Dampening the NOX5/ROS/c-Src pathway may ameliorate hypertension-associated vascular injury." (PMID 34320175, 2022). "Due to the regulatory role it exerts on cardiac tissue, NOX5 also seems to be involved in the development of heart attacks, hypertension, and cardiac hypertrophy." (PMID 36905456, 2023). "In hypertension, when NOX5 activity and oxidative stress are increased, these processes are up-regulated influencing vascular dysfunction in hypertension." (PMID 34320175, 2022). "Here, in human hypertension, we corroborate experimental evidence that VSMC NOX-derived ROS generation is increased, and clearly demonstrates that NOX5 up-regulation is a major underlying trigger." (PMID 34320175, 2022). "There is still a paucity of information on the molecular mechanisms that regulate vascular NOX5 and the downstream signalling pathways and networks through which NOX5-ROS mediate effects, particularly in human hypertension, is elusive." (PMID 34320175, 2022).
Hypertension (continued). "Following our observation that in HT NOX5/c-Src affects several signalling pathways, we questioned the role of NOX5 and c-Src in actin polymerization and cellular migration in hypertension." (PMID 34320175, 2022). "We corroborate experimental evidence that NOX-derived ROS generation is increased in human VSMCs and demonstrate that in human hypertension NOX5 up-regulation is a major trigger of VSMC dysfunction." (PMID 34320175, 2022). "It was also reported that endothelial Nox5 promotes NO-cGMP signaling dysfunction and hypertension in mice." (PMID 35740870, 2022). "On the other hand, NOX5 inhibition in patient-derived VSMCs prevented Ang II-mediated cell migration, suggesting a role of this axis in hypertension." (PMID 36358519, 2022). "Conversely, endothelial NOX1, NOX2, and NOX5 contribute to impaired vascular function, endothelial nitric oxide synthase (eNOS) uncoupling, and adverse vascular remodeling and hypertension." (PMID 36139898, 2022). "Molecular mechanisms linking NOX5 and downstream targets involve redox-sensitive c-Src, which is hyperactivated in hypertension." (PMID 34320175, 2022). "Together our results define NOX5/ROS/c-Src as a novel signalling pathway in human VSMCs, a system that is augmented in hypertension contributing to VSMC cytoskeletal disorganization and vascular dysfunction." (PMID 34320175, 2022). "Our findings highlighting NOX5 together with NOX4 in VSMC dysfunction in hypertension have clinical relevance because these NOX isoforms have been identified as novel BP-related genes." (PMID 34320175, 2022). "Clinical studies have found that NOX5 is involved in the development of myocardial infarction, atherosclerosis, hypertension, and aortic aneurysm and aggravates myocardial remodeling." (PMID 36407440, 2022). "While we cannot exclude a potential contribution of leukocytic NOX5 on hypertension in aged animals in our in vivo experiments, a contribution of adhering leukocytes is unlikely in our ex vivo experiments." (PMID 33170835, 2020). "Mechanistically, mice expressing human Nox5 in endothelial cells developed—upon aging—severe systolic hypertension and impaired endothelium-dependent vasodilation due to uncoupled NO synthase (NOS)." (PMID 33170835, 2020). "NOX5-dependent hypertension, however, appears to be disease relevant as this molecular mechanism also leads to or aggravates hypertension-associated clinical outcomes, stroke, myocardial infarction, and renal failure." (PMID 33170835, 2020). "This differential Nox5 expression in hypertension was attributed to an abnormal renal dopaminergic system." (PMID 30334629, 2019). "Comprehensive Nox5 phenotyping in patients with hypertension is needed to better clarify the potential importance of Nox5 as a pathophysiological factor in cardiovascular disease." (PMID 30334629, 2019). "On the other hand, under certain conditions, NOX4 has been suggested to be vasoprotective and the increase in VSMC expression, we observed in hypertension may represent a compensatory response to NOX5 up-regulation." (PMID 34320175, 2022). "Recent studies have shown that NOX5, a gene newly associated with hypertension, ameliorates abnormal VSMC proliferation, inhibits oxidative stress, and attenuates hypertensive complications through the NOX5/ROS/c-Src signaling pathway (redox-sensitive protein)." (PMID 36407440, 2022). "Increasing evidence supports a role for NOX5 in hypertension." (PMID 34320175, 2022). "Nox5 knock-in (KI) mice represent the first mechanism-based animal model of hypertension." (PMID 33170835, 2020). "Induction of NOX5 in smooth muscle cells does not cause hypertension per se but correlates with advanced atherosclerotic lesions, and diseased coronary arteries show high NOX5 expression and activity." (PMID 33170835, 2020).